TCN2 (transcobalamin 2)
Description:
Primary vitamin B12-binding and transport protein. Delivers cobalamin to cells.
Synonyms: TC-2; TC II; TCII; TC2; D22S676; D22S750; II; TC
Tractability: Small molecule: a structure with a bound ligand is known. Antibody: UniProt places it where antibodies can reach, with high confidence; its Gene Ontology location is reachable by antibodies, with high confidence; UniProt predicts a signal peptide or a membrane-spanning region.
Gene: Protein-coding gene on chromosome 22 (30,607,003 to 30,627,631, forward strand). Ensembl gene ENSG00000185339.
Subcellular location: Secreted
Subcellular location (Human Protein Atlas): Cytosol; Predicted to be secreted
Pathways (Reactome):
Disease: Defective CD320 causes MMATC; Defective TCN2 causes TCN2 deficiency
Metabolism: Transport of RCbl within the body
Gene Ontology:
Molecular function: cargo receptor ligand activity; cobalamin binding; protein binding; molecular carrier activity
Biological process: cobalamin transport
Cellular component: extracellular region; lysosomal lumen; plasma membrane; external side of plasma membrane
Genetic constraint (gnomAD): Loss-of-function variants: 34 observed, 50.99 expected, observed/expected ratio (o/e) 0.67, 90% interval 0.51 to 0.89. The synonymous counts are far from expectation, so gnomAD's model fits this gene poorly and the ratio says little. Missense variants: 652 observed, 555.56 expected, observed/expected ratio (o/e) 1.17, 90% interval 1.1 to 1.25. Synonymous variants: 283 observed, 225.72 expected, observed/expected ratio (o/e) 1.25, 90% interval 1.14 to 1.38.
Gene-disease validity (ClinGen):
ClinGen rates the evidence that TCN2 causes each of these diseases.
transcobalamin II deficiency (autosomal recessive): Definitive. Transcobalamin deficiency (TC) is a disorder of cobalamin transport that usually presents during the first few months of life and is characterized by megaloblastic anemia, failure to thrive, vomiting, weakness and pancytopenia.
Homologues: Orthologues: chimpanzee TCN2 (98% identical), macaque TCN2 (95% identical), dog TCN2 (76% identical), guinea pig TCN2 (75% identical), rabbit TCN2 (75% identical), mouse Tcn2 (74% identical), pig TCN2 (73% identical), rat Tcn2 (73% identical), tropical clawed frog tcn2 (39% identical), zebrafish tcn2 (30% identical), Drosophila melanogaster CG3556 (20% identical). Paralogues in human: TCN1 (28% identical), CBLIF (25% identical).
Diseases named in the same sentence as TCN2 in open-access papers:
TCN2 is named in the same sentence as 128 diseases in open-access papers, as found by Europe PMC text mining. Sharing a sentence is not in itself a finding about the gene and the disease. The quoted sentences say what the papers report.
vitamin B12 deficiency (7 papers, 2012 to 2025). A disease characterized by low serum levels of vitamin B12, either inherited or acquired. "For rs1801198 in TCN2, in Caucasian homozygotes, Vitamin B12 levels rose by 15%, while in Arabs, homozygosity was linked to 5.6 times higher odds of Vitamin B12 deficiency." (PMID 39861372, 2025). "TCN2 encodes a member of the vitamin B12-binding protein family, which binds cobalamin and mediates its metabolism, and an association between TCN2 and vitamin B12 deficiency has been widely reported by GWAS studies." (PMID 38448893, 2024). "In infants presenting with unexplained non‐specific neurological symptoms, irrespective of classical signs of vitamin B12 deficiency, evaluation for TCN2 defect should be considered." (PMID 37800653, 2023).
Pancytopenia (5 papers, 2015 to 2024). An abnormal reduction in numbers of all blood cell types (red blood cells, white blood cells, and platelets). "In a case series of 3 patients with ASD with transcobalamin deficiency/transcobalamin II (TCN2) mutations (one patient had metabolic acidosis and pancytopenia), cB12 intramuscular injections (1 mg once or twice weekly) were started along with carnitine." (PMID 34442428, 2021). "We report the case of an infant with TCN2 deficiency who presented severe pancytopenia and long-lasting acute respiratory distress syndrome (ARDS) secondary to immune reconstitution inflammatory syndrome (IRIS) and combined Cytomegalovirus (CMV) and Pneumocystis jirovecii (PJ) infection." (PMID 39201925, 2024). "In conclusion, IEM, such as TCN2 deficiency, should be considered in infantile pancytopenia." (PMID 39201925, 2024). "Clinical presentations of TCN2‐related disorders include pancytopenia, megaloblastic anemia, failure to thrive, diarrhea, psychomotor regression, and, in rare cases, epilepsy." (PMID 37800653, 2023). "Patients with TCN2 deficiency, regardless of mutation types, classically present before 1 year of age with failure to thrive, digestive symptoms and recurrent infections secondary to pancytopenia." (PMID 39201925, 2024).
inflammatory bowel disease (4 papers, 2012 to 2025). A spectrum of small and large bowel inflammatory diseases of unknown etiology. "Furthermore, TCN2 levels in peripheral blood monocytes of patients with various inflammatory bowel diseases including shigellosis, ulcerative colitis, and Crohn’s were 3-4 times higher than those measured in healthy normal patients, with levels decreasing in the setting of clinical improvement." (PMID 39493449, 2024).
megaloblastic anemia (4 papers, 2013 to 2026). Anemia characterized by the presence of unusually large erythroblasts in the bone marrow called megaloblasts. "Transcobalamin II (TCN2) deficiency is a rare autosomal recessive metabolic disorder that impairs vitamin B12 transport and can present with megaloblastic anemia and neutropenia, often mimicking hematologic diseases such as myelodysplastic syndrome (MDS)." (PMID 42038245, 2026). "Tcn2 deficiency led to intracellular VB12 deficiency which contributed to nervous system deterioration and megaloblastic anemia." (PMID 35720307, 2022). "Infants with TCN2 defect may present with megaloblastic anemia, feeding difficulties, developmental delay, microcephaly, failure to thrive, hypotonia, lethargy, irritability, involuntary movements, focal or multifocal seizures, and cerebral atrophy." (PMID 37800653, 2023).
Obesity (4 papers, 2014 to 2025). Accumulation of substantial excess body fat. "This study revealed that the TCN-2 gene polymorphism (776C>G) increases susceptibility to obesity and may lead to other related complications or metabolism-related disorders." (PMID 37240829, 2023). "This analysis showed that some proteins, such as COL1A1, COL6A3, FABP4, LEP, LGALS1, and THBS4, are obesity-specific, and GDF15, LPL, MCFD2, REG1A, REG1B, and TCN2 are T2D-specific." (PMID 38732002, 2024).
ulcerative colitis (4 papers, 2008 to 2025). An inflammatory bowel disease involving the mucosal surface of the large intestine and rectum. "We evaluated the association of the polymorphisms of MTHFR, MTR, MTRR and TCN2 genes with ulcerative colitis in Central China." (PMID 18700049, 2008). "Moreover, TCN2 rs1801198 and rs9606756 variations were significantly correlated with ulcerative colitis." (PMID 36275653, 2022).
ischemic stroke (3 papers, 2011 to 2021). A stroke disorder caused by obstruction of blood flow to the brain, due to thrombotic (local blood clot formation) or embolic (due to a blood clot or other material traveling from another site) event. "The total number of risk alleles on MTRR rs16879248, SHMT1 rs11868708, TCN2 rs1173570 showed a cumulative effect on ischemic stroke." (PMID 27822905, 2017). "Our study suggested that deficiency of both folate and vitamin B12 levels, caused by a combination of genetic variations at SHMT1, MTRR and TCN2, may jointly increase ischemic stroke risk." (PMID 21935458, 2011). "SNP analysis from the initial study suggested 3 risk variants in the MTRR, SHMT1 and TCN2 genes which were moderately associated with ischemic stroke risk, independent of known stroke risk factors." (PMID 21935458, 2011).
type 2 diabetes (3 papers, 2012 to 2024). "On the other hand, in OW/OB individuals, MTHFD1-rs1076991 (OR = 0.81 (95% CI 0.69–0.95) P = 0.01) and TCN2-rs1801198 (OR = 0.85 (95% CI 0.72–0.99), P = 0.04) showed nominal association with type 2 diabetes." (PMID 21960995, 2012). "Abnormal digestion and absorption of vitamins are closely associated with the development of diabetic gastroenteropathy, and previous studies have shown that vitamin deficiency is a risk factor for gastroparesis in patients with type 2 diabetes, and Tcn2 is a transporter protein for vitamin B12." (PMID 39211388, 2024).
anemia (2 papers, 2025 to 2026). A reduction in the number of red blood cells, the amount of hemoglobin, and/or the volume of packed red blood cells. "This case highlights the importance of considering rare metabolic disorders such as TCN2 deficiency in pediatric patients with unexplained anemia and neutropenia, and underscores the value of early recognition, genetic diagnosis, and long-term management." (PMID 42038245, 2026). "Mutations in the transcobalamin II (TCN2) gene disrupt vitamin B12 transport from the bloodstream to cells, causing severe anemia and neurological dysfunction, typically manifesting in infancy." (PMID 40444179, 2025).
bipolar disorder (2 papers, 2016). A disorder of the brain that causes unusual shifts in mood, energy, activity levels and the ability to carry out day-to-day tasks. "Among these six CpG-regulating genes, DPYSL2 is known to be associated with schizophrenia and bipolar disorder; while TCN2 is associated with various disorders including Alzeimer’s disease, vascular disease, and certain cancers (e.g., brain and colorectal)." (PMID 27326381, 2016).
developmental delay (2 papers, 2023). "Severe truncal hypotonia, neurologically significant developmental delay, and hypogammaglobulinemia have also been linked to TCN2 deficiency." (PMID 37800653, 2023). "Transcobalamin II (TCN2) defect is a rare metabolic disorder associated with a range of neurological manifestations, including mild developmental delay, severe intellectual disability, ataxia, and, in some cases, seizures." (PMID 37800653, 2023).
folate deficiency (2 papers, 2019 to 2023). A nutritional condition produced by a deficiency of FOLIC ACID in the diet. "Folate deficiency and TCN2 polymorphisms are both associated with increased homocysteine; thus, hyperhomocysteinemia represents a potential mechanism for congenital heart defects." (PMID 36672920, 2023).
immune deficiency (2 papers, 2019 to 2024). "The mechanisms underlying immunodeficiency in MMA are not fully understood, but case series of children with TCN2 deficiency have reported severe opportunistic infections including PJ pneumonia." (PMID 39201925, 2024).
malaria (2 papers, 2024 to 2025). Malaria is a serious and sometimes fatal disease caused by a parasite that commonly infects a certain type of mosquito which feeds on humans. "Our predictions here that heme biosynthesis is reduced in IECMs are consistent with our former hypothesis that the TCN2 c.776GG genotype produces a higher risk of severe malaria related to cobalamin‐related decreased heme synthesis." (PMID 40790789, 2025). "TCN2 was also elevated in the setting of various infectious diseases including malaria and typhus, supporting its role as a possible acute phase reactant." (PMID 39493449, 2024). "We previously showed that the TCN2 c.776GG genotype is twofold more frequent in Afro‐African individuals with severe malaria than in other Afro‐Africans exposed to malaria, with a Hardy–Weinberg disequilibrium of TCN2 genotype distribution recorded only in patients with severe malaria." (PMID 40790789, 2025).
multiple myeloma (2 papers, 2022 to 2024). "Carmel and Hollander found very high concentrations of TCN2 in patients with chronic lymphocytic leukemia, multiple myeloma, and other types of proliferative cancers." (PMID 36364737, 2022). "In this regard, increased TCN2 levels were previously reported in patients with a variety of inflammatory and lymphoproliferative disorders, including those diagnosed with multiple myeloma and Waldenstrom macroglobulinemia experiencing overproduction of immunoglobulins (hyperglobulinemia)." (PMID 39493449, 2024).
osteoporosis (2 papers, 2020 to 2026). A condition of reduced bone mass, with decreased cortical thickness and a decrease in the number and size of the trabeculae of cancellous bone (but normal chemical composition), resulting in increased fracture incidence. "Furthermore, specific allele combinations of CD320, TCN2, SLC19A1, and SLC19A2 may contribute to increased susceptibility to osteoporosis and OVCF." (PMID 32498429, 2020). "In the present study, we explored possible associations between SNPs located in the 3 ́–UTR of the CD320, TCN2, SLC19A1, and SLC19A2 genes and osteoporosis and OVCFs in 301 postmenopausal women." (PMID 32498429, 2020). "Our analyses therefore suggest that the allelic combinations of CD320, TCN2, SLC19A1, and SLC19A2 genes could play a role in the pathogenesis of osteoporosis and OVCF." (PMID 32498429, 2020). "The genotype and allele frequencies of the CD320 rs9426C>T, TCN2 rs10418 C>T, SLC19A1 rs1051296 G>T, and SLC19A2 rs16862199 C>T SNPs were compared between control subjects and osteoporosis patients with or without OVCF." (PMID 32498429, 2020).
Parkinson disease (2 papers, 2016 to 2023). A progressive degenerative disorder of the central nervous system characterized by loss of dopamine producing neurons in the substantia nigra and the presence of Lewy bodies in the substantia nigra and locus coeruleus. "The decreased concentration of CSF TCN2 in Parkinson’s disease was probably caused by disturbed lysosomal acidification and protease inhibition, except that severe deficiency of VB12 was also linked to cognitive decline." (PMID 37684700, 2023).
Stroke (2 papers, 2011 to 2014). Sudden impairment of blood flow to a part of the brain due to occlusion or rupture of an artery to the brain. "In the same VISP population, our group previously detected associations between genetic variants of the related gene, TCN2, and recurrent stroke risk." (PMID 25147783, 2014).
alopecia (1 paper, 2024). Hair loss usually from the scalp. "In addition, TCN2 expression was found to be associated with certain symptoms such as alopecia, elevated urinary proteins (>0.5 g/24 hours), arthritis, skin rash, light sensitivity, and various autoantibodies including anti-dsDNA, SM, RNP, histone, and nucleosome antibody." (PMID 38881906, 2024).
Arthritis (1 paper, 2024). Inflammation of a joint. "The elevated level of TCN2 is positively correlated with the severity of the disease and is associated with manifestations such as arthritis, kidney injury, and hair loss." (PMID 38881906, 2024).
asthma (1 paper, 2024). "Proteins TCN2,TNFRSF1B and C10orf54 were positively associated with the development of asthma (B>0); proteins PDGFD,INHBC and ANXA7 were negatively associated with the development of asthma (B<0)." (PMID 39318474, 2024).
Ataxia (1 paper, 2023). Ataxia refers to impaired coordination of voluntary muscle movement. "We present an extended family with a novel TCN2 mutation causing complex neurological manifestations, including progressive cognitive dysfunction, myoclonic epilepsy, and movement disorder – ataxia and tremor." (PMID 37800653, 2023).
autism spectrum disorder (1 paper, 2024). A spectrum of developmental disorders that includes autism, and Asperger syndrome. "ASD: Autism Spectrum Disorder; AT: Autoimmune Thyroiditis; MTHFR: Methylenetetrahydrafolatreductase; TCN1: Transcobalamin 1; TCN2: Transcobalamin 2; MTRR: Methionine synthase reductase; PEMT: Phosphoethanolamine N-Methyltransferase." (PMID 38807972, 2024).
autoimmune disease (1 paper, 2024). A disorder resulting from loss of function or tissue destruction of an organ or multiple organs, arising from humoral or cellular immune responses of the individual to their own tissue constituents. "Of utmost importance, increases in unsaturated TCN2 (APO-TCN2) have been reported in patients with active autoimmune diseases including systemic lupus erythematous (SLE), autoimmune hemolytic anemia, and dermatomyositis, with levels often correlating with disease activity." (PMID 39493449, 2024).
Autoimmune Thyroiditis (1 paper, 2024). "Two patients with autoimmune thyroiditis carry the heterozygous (CG) genotype, and one carries the homozygous (GG) genotype in the TCN2 polymorphisms." (PMID 38807972, 2024).
breast carcinoma (1 paper, 2024). "Numerous cellular clusters across many solid tumors revealed differential expression of TCN2 including non-small cell lung cancer (NSCLC), intrahepatic cholangiocarcinoma (ICC), breast cancer (BC), nasopharyngeal carcinoma (NPC), and skin cutaneous melanoma (SKCM), among others." (PMID 39493449, 2024).
cleft lip (1 paper, 2020). Congenital defect in the upper lip where the maxillary prominence fails to merge with the merged medial nasal prominences. "The four genetic missense variations 677C>T in MTHFR (rs1801133), 66A>G in MTRR (rs1801394), 776C>G in TCN2 (rs1801198), and 716 G>A in BHMT (rs3733890) have influence on protein function, and have been reported to be associated with cleft lip." (PMID 32124929, 2020). "Recently, many efforts have been made to find the genetic variants in folate pathway genes such as MTHFR (methylenetetrahydrofolate reductase), MTRR (Methionine synthase reductase), TCN2 (transcobalamin 2), and BHMT (betaine-homocysteine methyltransferase) and their susceptibility to cleft lip." (PMID 32124929, 2020).
colorectal cancer (1 paper, 2016). A primary or metastatic malignant neoplasm that affects the colon or rectum. "In another example, one local CpG site in body region was associated with the expression of TCN2, which is associated with Alzeimer’s disease and certain cancers including colorectal cancer." (PMID 27326381, 2016). "Interestingly, our results indicated a possible link of shared living environment and behavioral lifestyle in the regulation of TCN2 that belongs to the one-carbon metabolism pathway, which has been associated with the risk for colorectal cancer." (PMID 27326381, 2016).
Hypertension (1 paper, 2019). The presence of chronic increased pressure in the systemic arterial system. "TCN2 rs117353193 might serve as a protective factor in hypertension, and RNF213 rs9916351 might be a risk factor that is linked to increase BP level in Northeast Chinese population." (PMID 31815282, 2019). "In summary, our study suggests that the TCN2 rs117353193 gene polymorphism might serve as protective factor in hypertension, and the RNF213 rs9916351 gene polymorphism might be an important risk factor that is linked to increase the level of BP among the population of northeast in China." (PMID 31815282, 2019). "The present study was conducted to examine the association of MTHFR rs1801133, rs1801131, rs9651118, TCN2 rs117353193 and RNF213 rs9916351 gene polymorphisms with the risk of hypertension and BP in Northeast Chinese population." (PMID 31815282, 2019). "We aimed to evaluate the associations of MTHFR (rs1801133, rs1801131, rs9651118), TCN2 (rs117353193) and RNF213 (rs9916351) with hypertension and blood pressure (BP)." (PMID 31815282, 2019). "The present study was designed to investigate the association of MTHFR (rs1801133, rs1801131, rs9651118), TCN2 (rs117353193) and RNF213 (rs9916351) gene variants with the susceptibility of hypertension and BP among the population of northeast in China." (PMID 31815282, 2019). "Methylenetetrahydrofolate reductase gene (MTHFR), transcobalaminII (TCN2) and ring finger protein 213 (RNF213) are related to homocysteine (Hcy) level and are of great significance for hypertension." (PMID 31815282, 2019). "MTHFR rs9651118, TCN2 rs117353193 and RNF213 rs9916351 were recently revealed as the novel susceptibility loci for MMD by a genome-wide association study, no studies were conducted concerning the link to hypertension, and more evidences are needed to support our results." (PMID 31815282, 2019).